KRTAP3-4P (keratin associated protein 3-4, pseudogene)
Synonyms: KAP3A; KRTAP3P1
Gene: Unprocessed pseudogene on chromosome 17 (41,004,481 to 41,004,760, reverse strand). Ensembl gene ENSG00000226776.
Diseases named in the same sentence as KRTAP3-4P in open-access papers:
KRTAP3-4P is named in the same sentence as 1 disease in open-access papers, as found by Europe PMC text mining. Sharing a sentence is not in itself a finding about the gene and the disease.
KRTAP3-4P shares sentences with these, for which no sentence is quoted: breast carcinoma (1 paper).